KRAS (KRas proto-oncogene, GTPase)
Diseases named in the same sentence as KRAS in open-access papers (continued):
Sharing a sentence is not in itself a finding about the gene and the disease.
tumor (continued). "In a CCSPCre/LSL-KrasG12D mouse model of KRAS-driven NSCLC, IL6 induced the proliferation of tumor cells and facilitated an immunosuppressive microenvironment by enhancing the polarization of alternatively activated macrophages and recruitment of MDSCs." (PMID 34944848, 2021). "In these studies, lentivirus was used to deliver Cre-recombinase to drive the expression of KRAS[Gly12Asp] whilst simultaneously delivering CRISPR guides to disrupt SIK1 and SIK3 expression, which accelerated tumour growth." (PMID 33861845, 2021). "They used ddPCR, focusing on alterations in KRAS, BRAF and PIK3CA, for ctDNA detection prior and after tumor resection in localized PDAC." (PMID 33673558, 2021). "Another pathway activated by oncogenic KRAS is RAS-like (RAL)A–RALB, which is essential for tumor initiation, endocytosis, exocytosis, and subsequent resistance to chemotherapy and radiotherapy." (PMID 34064352, 2021). "This research was aimed at considering the potential clinical usefulness KRAS and HRAS gene as tumor markers playing a role in the diagnosis (the differentiation between malignant and benign disease or histological subtype) as well as predictive biomarkers." (PMID 33549031, 2021). "The mRNA expression level and prognostic significance of KRAS, BRAF, and KIT were checked using the UALCAN database, in the heatmap representation, normal tissue (n = 1), primary tumor (n = 104), and metastatic cases (n = 368)." (PMID 34769348, 2021). "GEO datasets validated that the 6 genes (SHC1, FKBP4, NRAS, PRKCD, KRAS, ADCY9) had different expression between tumor tissues and adjacent normal tissues in LUAD, and 3 genes (FKBP4, KRAS, ADCY9) were related to the prognosis of LUAD." (PMID 33936178, 2021). "Another interesting tumor type for the combination treatment with APR-246 and ASNase is KRAS-driven non-small-cell lung cancer (NSCLC)." (PMID 34267184, 2021). "In NSC290956-treated mice, the ERK and AKT phosphoproteins in tumor sections were markedly decreased, which confirmed that the in vivo efficacy of NSC290956 is correlated with the impairment of KRas-mediated signaling." (PMID 35069209, 2021). "Overall, although activation of autophagy is frequently observed in PDAC and other tumour types with oncogenic activation of the ERK/MAPK pathway, the dependency of KRAS-mutant tumours on autophagy seems model- and tumour-type dependent." (PMID 32929194, 2021). "The importance of KRAS stability in CSC activation was also demonstrated by work on WD repeat protein 76 (WDR76), an E3 ligase that destabilises RAS, thereby acting as a tumour suppressor." (PMID 33802849, 2021). "The authors noted increased influx of immune cells into the tumor and tumor regression upon oncogenic inactivation, and identified BRAF and MYC as key mediators of KRAS-induced immune evasion." (PMID 34957115, 2021). "Hence, the strong predictive power of Wnt and TAM pathway SNPs in mCRC may lie in their complex interactions modulating the tumor microenvironment and angiogenesis, resulting in similar results observed in KRAS wildtype and KRAS mutant subgroups treated with bevacizumab-based chemotherapy." (PMID 34108518, 2021).
tumor (continued). "Considering that the observed decline of mutated KRAS alleles in ctDNA upon CET treatment cessation was not consistently accompanied with tumor shrinkage, another intriguing possibility may also in part explain a proportion of the observed discrepancy between ctDNA and primary tissue mutation data." (PMID 34271981, 2021). "Activation of KRAS induces the AKT-mTOR or RAF-ERK-pathways, which have an important role in modulating tumor microenvironment in EC." (PMID 34725559, 2021). "Following the in vitro observations in KRas-mutant NSCLC cells, the effect of NSC290956 was further evaluated in a subcutaneous tumor model using H358 tumor xenograft." (PMID 35069209, 2021). "When KRAS or MEK or mTORC1/2 are inhibited individually in PDAC cells, tumor cell plasticity and rapid adaptation to stress activates compensatory pathways and favors the survival of tumor cells." (PMID 34805167, 2021). "However, this KRAS mutation was not identified in the tumor tissue." (PMID 33915745, 2021). "Eleven patients (6 with KRAS-mutant and 5 with RAS wild-type CRC) with tumor specimens were enrolled in this study." (PMID 34347396, 2021). "Specific comparison of EGFR, KRAS and BRAF findings were compared following the analysis of tumor tissue, PB cfDNA, MPE cell pellets (cell-blocks) and cell-free MPE samples from the same probands." (PMID 34257581, 2021). "MiR-206 has also directly targeted the oncogenes KRAS and annexin a2 (ANXA2), acting as a tumor suppressor in various types of cancer by blocking cell cycle progression, cell proliferation, migration, and invasion." (PMID 34900997, 2021). "EVs can affect the extracellular matrix (ECM) by modulating tumor immunity responses and can even transfer active oncogenes, e.g., EGFR or the mutant form of KRAS." (PMID 34684727, 2021). "Novel second generation KRAS G12C inhibitors are under development in preclinical models, that consist of tri-complex inhibitors of the oncogenic GTP-bound form of KRAS G12C (ON) that overcome RTK-mediated escape mechanisms and lead to tumor regressions." (PMID 35083149, 2021). "Therefore, wild-type KRAS might serve as a tumour-suppressor gene in the presence of mutant KRAS." (PMID 34822010, 2021). "Another phase I/II trial involved 129 KRAS-G12C–mutant cancer patients, in which 32.2% of NSCLC, 7.1% of CRC, and 14.3% of other tumor patients showed an objective response to sotorasib." (PMID 34607583, 2021). "Patient triage could be performed by a quick assessment of tumor burden and testing of biomarkers with predictive and prognostic value (such as immunohistochemistry for mismatch repair proteins; sequence variation analysis for KRAS [GenBank 3845], NRAS [GenBank 4893], and BRAF)." (PMID 34495337, 2021). "In addition to KRAS, both HRAS and NRAS have all been reported to dimerize, but the biologic effects of RAS dimerization and whether a similar mechanism underlies the tumor suppressive functions of WT HRAS and NRAS are untested." (PMID 33924994, 2021). "Apart from KRAS and PIK3CA, other genes preferentially altered in the right-sided primary tumor sites, such as PRKDC, ERBB3, BCLAF1 and NOTCH1, have been reported to be correlated with poor prognosis or migration in CRC." (PMID 34281583, 2021). "Treatment with the combination of KRAS G12C inhibitor, PI3K inhibitor, and SHP2 inhibitor resulted in tumor regression in mouse models of acquired resistance to KRAS G12C inhibitor, AMG510." (PMID 34830757, 2021). "In this review, we first describe the heterogeneity that is at the center of the dependency to mutant KRAS and the epithelial-to-mesenchymal transition (EMT) of these tumor cells." (PMID 34680229, 2021).
tumor (continued). "However, the concordance rate of KRAS and BRAF mutation analysis was 94% and 100% in a previous report, suggesting only a marginal influence of whether the sample for mutation analysis is taken from the primary tumor or the metastasis." (PMID 31571052, 2020). "On the other hand, the expressions of KRAS and EGFR in primary tumor tissues were shown to be significantly higher than those in adjacent normal tissues (p < 0.001)." (PMID 33552955, 2020). "Based on these scientific findings, we were motivated to analyze the potential role of ACAA1 in KRAS-mutant NSCLC and elucidate the correlation of ACAA1 with the immunosuppressive phenotype in the tumor microenvironment." (PMID 33194642, 2020). "In preclinical analyses, treatment with AMG 510, which is the first identified KRAS (G12C) inhibitor, led to the regression of KRASG12C tumors and improved the anti‐tumor efficacy of chemotherapy and targeted agents." (PMID 32724874, 2020). "TBK1.DF_DN is a gene set composed of genes down-regulated as a combination of an over-expressed oncogenic form of KRAS and the suppression of TBK1, a kinase that regulates cell proliferation, apoptosis, autophagy, and anti-tumor immunity." (PMID 32850701, 2020). "The worse prognosis in subjects whose tumor was submitted for KRAS and BRAF mutation analysis compared with those not analyzed could be explained by a need for more antitumor treatment in addition to CRS and HIPEC, where patients with unfavorable prognostic signs are selected for mutation analysis." (PMID 31571052, 2020). "Although numerous studies on KRAS-mutant type NSCLC have been conducted, new oncogenic or tumor suppressive genes need to be detected because a large proportion of NSCLC patients does not respond to currently used therapeutics." (PMID 32728173, 2020). "During the previous decades, numerous genetic variations have been described in NSCLC, including epidermal growth factor receptor (EGFR), KRAS and anaplastic lymphoma kinase (ALK), as the most commonly altered oncogenes acting as tumor driver genes." (PMID 33022831, 2020). "Further, the gene expression profiling of the tumour exhibited a higher level of EPCAM, CK20, KRAS, AKT1, BRAF and CD133 expression, while lower levels of expression were observed in NANOG, MMP9 and APC genes." (PMID 33092235, 2020). "Oncogenes, such as cMYC or KRAS, and genes involved in drug-resistance such as multi-drug resistance 1 (MDR1) are tempting targets for tumor therapy using RNAi." (PMID 32151052, 2020). "Reports show that KRAS and MYC collaborate in shaping the tumor microenvironment and work together to support tumor growth while avoiding immune recognition." (PMID 33081056, 2020). "The presented study demonstrates dose-dependent radiation-responsiveness of a KRAS-driven PDA cell line in conventional radiation biology endpoints such as clonogenicity and in the current concept of irradiation-induced tumour cell immunogenicity." (PMID 31959787, 2020). "A prominent example is combination of covalent KRAS G12C inhibitor MRTX849 with EGFR, mTOR, or SHP2 inhibitors which were shown to be more effective than monotherapy in tumor models." (PMID 32715349, 2020). "KRAS signaling and EMT pathways which were considered to be able to promote tumor growth and metastasis were found upregulated in all low‐purity groups." (PMID 33030278, 2020).
tumor (continued). "KRAS knockdown by two different targeting shRNAs abolished tumor sphere formation in MiaPaCa2 and MDA-MB231 cells, confirming the importance of KRAS in the self-renewal of these cells." (PMID 32561852, 2020). "The anti-tumor effects of deltarasin were also validated and confirmed in vivo applying an orthotopic HCC mouse model and KRAS inhibition by deltarasin markedly enhanced sorafenib-induced tumor cell apoptosis and inhibition of proliferation in HCC cells." (PMID 31906510, 2020). "The fact that DDR1 expression level is not restricted to any specific CMS subclass and that its tumor-promoting function is KRAS mutation-independent suggests that DDR1 inhibitors could be active in all CRC subtypes, including CMS3 tumors for which the therapeutic options are limited." (PMID 32117772, 2020). "Focusing on tumor BC03, pathways for G2M checkpoint and KRAS signaling are upregulated in lymph node metastasis Clone BC03LN_1, while pathways for estrogen response and apoptosis are downregulated, indicating a more invasive phenotype." (PMID 31937348, 2020). "Significantly lower methylation was recorded in the G0-tumor free control samples (14.4%; n = 7) as well as wildtype tumor samples (22.8%; n = 78) compared to EGFR/KRAS mutant samples (28.6%; n= 39) (p = 0.050 and p = 0.046; respectively)." (PMID 32605217, 2020). "Hence, we investigated whether KRAS induces ALDH1L1 to promote tumor growth." (PMID 32481524, 2020). "In the present study, we employed massively parallel sequencing to detect genetic changes in six major driver genes including EGFR, KRAS, NRAS, BRAF, ALK and ROS1 in tumour tissues from 350 NSCLC patients in Vietnam." (PMID 32066856, 2020). "Intracellularly, G12D mutant KRAS should be able to bind to the corresponding MHC I molecules and display on the CT26 cell surface, making it possible for CT26 tumor cells to be lysed by cytotoxic lymphocytes." (PMID 32903495, 2020). "Thus, inhibition of PTPN2 could suppress KRAS cancer, whereas enhancing tumor immunity." (PMID 33122197, 2020). "Some of these diverse mechanisms for calmodulin to regulate KRas and Rac1 GTPases could provide therapeutic opportunity in cancer pathophysiology, in particular where aberrant KRas signalling drives Rac1-dependent activities that contribute to tumour progression." (PMID 32456244, 2020). "According to the calculated tumor population rate, which was determined using the VAF and the copy number (CN)-status for KRAS, the cohort was divided into nine patients with clonal KRAS-mutations and seven patients with subclonal KRAS-mutations at diagnosis." (PMID 32079091, 2020). "Moreover, inhibition of activated KRAS could delay tumor progression both in vitro and in vivo." (PMID 33122197, 2020). "On the one hand, receptor for advanced glycation end products (RAGE) binding to KRAS fuels the activation of HIF-1α and promotes tumor development and glycolysis in PDAC under hypoxia." (PMID 33256814, 2020).
tumor (continued). "For example, in tumor IGC-11-1130, four samples were tested and all had alterations in the KRAS pathway." (PMID 32424208, 2020). "EGFR and KRAS genes were classified as oncogenes and STK11, RB1 and MGA genes were classified as tumor suppressors." (PMID 32998690, 2020). "Here, we show the tumor-promoting function of a cell cycle-related protein, PIERCE1, in KRAS-mutant NSCLC." (PMID 32728173, 2020). "Our results identify strong contributions of epithelial-to-mesenchymal transition (EMT), classical tumor-promoting (such as E2F, KRAS, MYC, mTORC1, and TGFB1 signaling) and immune-related pathways in the tumor epithelium of COSCC." (PMID 33142242, 2020). "Dramatic tumor-inhibitory effects of DTSP, which is easily prepared, make it a more attractive strategy against KRAS G12D tumors." (PMID 32903495, 2020). "In the GSEA, a high expression of GABRD was positively correlated to several gene sets that are closely related to carcinogenesis and tumor progression, including EMT, angiogenesis, hedgehog signaling, KRAS signaling, Wnt-β-catenin signaling, and UV response." (PMID 33336074, 2020). "Proinflammatory pathways are upregulated in KRAS-dependent tumors, including increased production of the chemokines IL-1β, CCL7, and CCL2, as a result of crosstalk between KRAS-mutant tumor cells and host myeloid cells." (PMID 33335263, 2020). "Our study is the first to target the KRAS-G12S mutant with the CRISPR/Cas9 and dCas9-KRAB systems for inhibition of tumor growth." (PMID 32308773, 2020). "A tumor-suppressive function is exerted by IGF2BP1 too, which inhibits KRAS, CDC34, and MYC expression and promotes apoptosis." (PMID 33238574, 2020). "In a KRAS-driven skin squamous cell carcinoma mouse model, deletion of the PAK1 gene led to decreased tumor initiation and progression, thus indicating an important role for PAK1 in Ras signaling." (PMID 32648136, 2020). "The molecular characterisation of CTCs to assess KRAS, BRAF and PIK3CA status has been achieved, which showed discordance of their status between the primary tumour and CTCs." (PMID 33209110, 2020). "The oncogenes Kristen rat sarcoma 2 viral oncogene homolog (KRAS), epidermal growth factor (EGF) and SRC are transferred by exosomes to recipient tumor cells to promote tumor invasion." (PMID 33396739, 2020). "Therefore, a substantial number of studies implicate that inhibition of PKC-mediated phosphorylation of KRas at the Ser181 residue, possibly in combination with agents that block calmodulin-mediated PI3K/Akt activation, could be a potential therapeutic target for KRAS-driven tumours." (PMID 32456244, 2020). "Conversely, gain in KRAS, PIK3CA and SMAD4 alterations and scarce granzyme-B+ T-cells infiltration were observed when the tumor evolved towards a poly-metastatic spread." (PMID 33096795, 2020). "Thus, because only KRAS fragments in plasma were validated with ddPCR, we hypothesized that KRAS mutant fragments in plasma, as well as the concentration of cfDNA, would be correlated with tumor burden in the liver." (PMID 32379795, 2020). "A previous study showed that oncogenic KRAS increases tumor PD-L1 expression and promotes CD8+ cells infiltration to the tumor stroma." (PMID 33194642, 2020). "Ninety percent of the tumours with these gene rearrangements were native KRAS, with a high proportion of MSI-H: 86.4%, 45.5% and 14.3% of the tumours with NTRK1, RET and ALK fusions, respectively." (PMID 32418154, 2020). "CRC cell lines with KRAS p.G13D (HCT-15 and HCT-116) were subcutaneously inoculated into the right flank of each nude mouse to establish a system for examining the anti-tumor activity of EMab-17 in xenograft models." (PMID 32839411, 2020).